KEAP1 (kelch like ECH associated protein 1)
Diseases named in the same sentence as KEAP1 in open-access papers (continued):
Sharing a sentence is not in itself a finding about the gene and the disease.
tumor (continued). "Under DAPT treatment, KEAP1-silenced cells did not in fact show significant variation in NOTCH and HES-1 protein levels or changes in the viability of tumor cells." (PMID 38791966, 2024). "When it came to alterations of several genes such as KEAP1 and PIK3CB, the tendency of discrepancy was unanimous in MVI/NMVI to recurrence/non-recurrence comparison, not only in tumor tissue but also in ctDNA analysis." (PMID 35155229, 2022). "In the context of tumor, however, we found a significantly negative relationship between SETD7 and KEAP1 both in the TCGA database and in experimental discoveries." (PMID 29212211, 2017). "Overall, The data show us that Keap1, Nrf2, PPIA, Prdx6 and CD147 were not correlated with tumor stage (T1 to T3), lymph node status (N0 to N1), pathological grade (GI to GIII) (P>0.05)." (PMID 24386210, 2013). "Spearman’s correlation analysis for the mRNA expression of NRF2 pathway genes in normal and tumor tissues from our institutional cohort also revealed high concordance in expression between DPP3 and NRF2 pathway genes, including NFE2L2, KEAP1, and NQO1 in tumors, but not in normal tissues." (PMID 37531267, 2023). "Consistent with the lack of effect of genetic Nrf2 activation by Keap1 knockdown, chronic intervention with TBE-31 (5 nmol/g body weight, orally, 3 days per week for 12 weeks, starting at week 8 of age) did not affect tumor development in Gstp+−/+−: ApcMin/+ mice." (PMID 34526660, 2021). "It was demonstrated in several human tumor cell lines cells that FOXO3 (but interestingly neither FOXO1 nor FOXO4) stimulates the transcription of the Keap-1 gene, regulating Keap-1 protein levels; of note, this FOXO3/Keap axis appears to exist in human but not murine cells." (PMID 28818793, 2017). "We have shown that the levels of IKKβ and BCL2 tend to be higher in tumor cell lines that have high basal NRF2 activity, suggesting that mutant or low/absent levels of KEAP1 may contribute to elevated IKKβ and BCL2 levels." (PMID 26301506, 2015). "Indeed, these workers have proposed that tumour cells with upregulated NRF2 have increased dependency on exogenous non-essential amino acids, and that depletion of non-essential amino acids in the microenvironment preferentially inhibits proliferation of MEFs lacking Keap1." (PMID 33276631, 2020).
neurodegenerative disease (50 papers, 2010 to 2025). A disorder of the central nervous system characterized by gradual and progressive loss of neural tissue and neurologic function. "Phosphorylation of Keap1 causes Nrf2 to migrate to the nucleus when cells it is exposed to neurodegenerative disease-induced oxidative stress." (PMID 37180724, 2023). "When cells are exposed to neurodegenerative disease-mediated oxidative stress, phosphorylation of Keap1 causes Nrf2 to migrate to the nucleus, where it binds to the small Maf protein and the antioxidant responsive element (ARE)." (PMID 34943071, 2021). "GSK-3 has more recently been shown to inhibit Nrf-2, independently of Keap1, but has long been implicated in the pathogenesis of several neurodegenerative diseases including AD." (PMID 28253260, 2017). "Studies have shown that KEAP1/PGAM5/AIFM1 mediated oxeiptosis may lead to neuron loss in neurodegenerative diseases by causing oxidative stress and mitochondrial dysfunction." (PMID 40371389, 2025). "Studies on nitrosative/oxidative stress and inflammatory responses in neurodegenerative diseases have also indicated the importance of the anti-oxidant pathway involving the Kelch-like ECH-associated protein 1 (Keap1)/Nuclear Factor Erythroid 2-Like 2 (NFE2L2, Nrf2)." (PMID 26505893, 2015). "The activation of the Keap1-Nrf2-ARE signaling pathway in neurodegenerative disease models has been shown to provide cellular antioxidant protection, reduce neuronal damage, and delay disease progression." (PMID 40371389, 2025). "The protective role of the antioxidant and cytoprotective Keap1/Nrf2 pathway has been discussed as a therapeutic target for treatment against many neurodegenerative diseases including ALS." (PMID 38906677, 2024). "Several reports have demonstrated how Nrf2 activation, through its release from binding to Keap1 protein, protects against oxidative stress in both in vitro and in vivo models of neurodegenerative disease, including 3NP-induced HD’s like disease in rats." (PMID 39327568, 2024). "Our findings provide compelling support for the use of direct Keap1-Nrf2 inhibitors for the treatment of neurodegenerative diseases, particularly AD." (PMID 28253260, 2017). "For the efficient medical applications of the Keap1-Nrf2 system for the treatment of neurodegenerative diseases, Nrf2 should be considerably expressed in the brain." (PMID 22046393, 2011). "As a gatekeeper of antioxidant and anti-inflammatory cell protection, the transcription factor Nrf2 is a promising therapeutic target for several neurodegenerative diseases, leading to the development of Nrf2 activators targeting Keap1-dependent and independent regulatory mechanisms." (PMID 40718467, 2025). "Therefore, interrupting the formation of Keap1/Nrf2 complex by targeting Keap1 becomes one potential approach to prevent neurodegenerative diseases." (PMID 33777321, 2021). "Recent advances in the development of direct inhibitors of the Keap1-Nrf2 binding domain may, therefore, enable the prevention of Nrf2 deficits in neurodegenerative diseases with minimal side-effects." (PMID 28253260, 2017). "Some antioxidant enzymes are regulated by the Keap1-ARE (Keap1 antioxidant response element) pathway, which is dependent on Nrf2, a transcription factor activated in oxidative stress situations that plays a key role in the central nervous system and neurodegenerative diseases." (PMID 34829724, 2021). "Both GSK-3 and Keap1 may, therefore, serve as valid candidates for mediating the inhibition of Nrf2 in neurodegenerative diseases, and their inhibition may enable the prevention of Nrf2 deficits, neuronal stress and degeneration specifically in these conditions." (PMID 28253260, 2017). "The activation of the KEAP1/Nrf2/ARE signaling pathway plays a pivotal role in preserving cellular redox homeostasis and serves as a protective measure against the onset of neurodegenerative diseases." (PMID 40298834, 2025).
neurodegenerative disease (continued). "The activation of the KEAP1/Nrf2/ARE signaling pathway plays a pivotal role in maintaining redox homeostasis and acts as a preventive measure against neurodegenerative diseases induced by oxidative stress." (PMID 40298834, 2025). "It has been suggested that p62 phosphorylation increases the sequestration of Keap1 into inclusions, thus facilitating NRF2-Keap1 dissociation and activation of NRF2 dependent gene response in PD and other neurodegenerative diseases." (PMID 34092244, 2021). "There are a number of other drug-like molecules with a similar mechanism of action as DMF, but they directly interfere with the Keap1/NRF2 interaction and show more prospects for targeting NRF2 in neurodegenerative diseases." (PMID 30337853, 2018). "At present, several studies indicate that the activation of Kelch-like ECH-associated protein 1/nuclear factor erythroid 2-related factor 2/antioxidant response element (Keap1/Nrf2/ARE) pathway has a certain neuroprotective effect in numerous cellular and animal models of neurodegenerative diseases." (PMID 35237381, 2022). "Taken together, our study identified a new Keap1 specific inhibitor, FUC, which could be used as a potential candidate in the prevention of neurodegenerative diseases." (PMID 33777321, 2021). "Alterations in Nrf2 and Keap1 expression and dysregulation of the Nrf2/ARE signalling program could contribute to the chronic motor neuron degeneration in ALS and other neurodegenerative diseases." (PMID 23050144, 2012). "Itaconate acts on Nrf2/Keap1 to exert antioxidant and anti-inflammatory effects, negatively modulates STING pathways to play an antiviral and bacterial infection role, and inhibition of ferroptosis can play a role in lipid peroxidation-related degenerative diseases." (PMID 35812373, 2022).
infection (40 papers, 2016 to 2025). The state of being infected such as from the introduction of a foreign agent such as serum, vaccine, antigenic substance or organism. "Some studies have shown that EBV can activate or maintain the NRF2 signaling pathway via LMP1 and KEAP1, enhancing the host’s antioxidant capacity and reducing oxidative damage caused by infection." (PMID 40302035, 2025). "In the primary human endometrial cells (“Endometrial cells”), infection with lv-pre-miR-941 led to an over 10 fold increase in the expression of mature miR-941, causing downregulation of Keap1 mRNA." (PMID 32102665, 2020). "Curcumin was observed to enhance the activities of antioxidant enzyme SOD, CAT, and GPx by upregulating the expression of Cu/Zn SOD, MnSOD, CAT, and GPx mRNA, which was associated with the Keap1/Nrf2 signaling pathway in grass carp following infection with Aeromonas hydrophila." (PMID 38666864, 2024). "Still, in the final stages of infection, KEAP1 may downregulate NRF2, decreasing the association with chromatin." (PMID 33826673, 2021). "Infection of K. pneumoniae reduced Nrf2, Keap1 and HO-1 expression and enhanced ROS production in bMECs." (PMID 39953606, 2025). "In bMECs, infection with K. pneumoniae induced oxidative stress, decreasing protein expression of Nrf2, Keap1 and HO-1 plus SOD activity, and increasing ROS concentrations." (PMID 39953606, 2025). "While we did not observe a statistically significant effect, knock-out of NFE2L2 showed a trend toward enhanced infection, whereas knock-out of the endogenous inhibitor KEAP1 strongly decreased infection." (PMID 38319076, 2024). "Firstly, trans-infection of KEAP-R483S can only reduce the binding force of KEAP1/NRF2, but KEAP1-R483S can still bind NRF2." (PMID 38100883, 2024). "Infection modestly increased KEAP1 mRNA in both WT and NRF2-/- cells, and treatment with all compounds led to a significant reduction, which appeared to be more pronounced in the NRF2-/- cells." (PMID 37459366, 2023). "Infection modestly raised KEAP1 mRNA expression in WT and XPO1 knock-down cells, but tended to downregulate the other analyzed mRNAs except HMOX1." (PMID 37459366, 2023). "The half-life of Keap1 was decreased at 72 hpi following treatment with ARP101, indicating ARP101-induced degradation of Keap1 at later stages of infection." (PMID 36939350, 2023). "Activation of the Nrf2/Keap1 axis through various mechanisms to regulate oxidative stress has been described from the infection of several viruses, including hepatitis C virus (HCV), HBV, influenza and HIV." (PMID 35139135, 2022). "There was a significant interaction between diet and infection for the antioxidant genes Hmox1 and Keap1, with PTS-PTSO inducing expression in infected mice that was significantly higher than for the other groups." (PMID 36290756, 2022). "In general, EIAV Rev-triggered activation of Nrf2/Keap1 axis following EIAV infection contributes to the host defenses against infection." (PMID 35139135, 2022). "Our results showed that down-regulated expression of Nrf2 signaling molecule and up-regulated levels of Keap1 mRNA in the muscle of turtles after infection." (PMID 33574492, 2021). "After the 30th day of infection, the activity of the Keap1/Nrf2/ARE system was decreased and its effector genes entailed increasing ROS production in the liver." (PMID 34093961, 2021). "For further confirmation, MA104 cells were silenced for Keap1 expression by Keap1 siRNA before checking the status of Nrf2 protein levels post RV-SA11 infection (9 hpi)." (PMID 32322337, 2020). "In the primary human endometrial cells antagomiR-941 infection similarly downregulated mature miR-941 expression, leading to an increase in Keap1 mRNA and protein levels." (PMID 32102665, 2020). "Inhibition of Nrf2 by lentiviral infection of Keap1, or knockout of Nrf2 by CRISPR-Cas9 gene editing, not only blocked iAs-induced HIF1α activation, but reduced the expression of the key stemness genes for the formation of CSCs also." (PMID 32226544, 2020).
infection (continued). "Given that the formation of the LC3-p62-Keap1 ternary complex on the autophagosome membrane directs Keap1 to degradation, we investigated the induction of p62 in the infection." (PMID 28959260, 2017). "Keap1 siRNA transfected BMM showed increased Mtb levels measured 5 days after infection." (PMID 40602278, 2025). "However, protein expression of Keap1 and HO-1 decreased with increasing infection time and was significantly lower than the Control group (P < 0.05)." (PMID 39953606, 2025). "Thus, under these infection-induced stress conditions, Keap1 undergoes oxidative modification, leading to a conformational change in the shape of the Keap1-Nrf2 complex, releasing Nrf2 from Keap1, which accumulates in the cytoplasm." (PMID 39000157, 2024). "When S. Typhimurium infected bone marrow macrophages, the protein expression of p62 and Nrf2 decreased and Keap1 increased 2 h after infection, but the protein expression of p62, Keap1 and Nrf2 returned to a level similar to the normal value 6 h after infection." (PMID 39886212, 2024). "In addition, we measured the expression levels of genes acting in a master regulator pathway of the redox status of the cells, modulated also by SA infection of bone cells, i.e., the Keap1-Nrf2 pathway." (PMID 34357987, 2021). "Kelch-like ECH-associated protein 1 is a negative regulator of Nrf2, and in the context of infection by Leishmania, we demonstrated that Keap1 is regulated after 18 h of infection in a PKR-independent manner (data not included)." (PMID 28959260, 2017). "However, during the early stages of L. pneumophila infection (1-2 h post-infection, hpi) to A549 lung cells, ubiquitination of p62 at residues Ser361/365/366, near the p62-KIR, by ubiquitin-linked phosphoribosyl (PR-Ub) prevents its binding to Keap1." (PMID 39763664, 2024). "The results demonstrated that ASFV-WT infection suppresses key genes involved in the Nrf2 signaling pathway, including GCLM, GCLC, Keap1, and NFE2L2 (Nrf2)." (PMID 39964001, 2025). "Briefly, Keap1, a specific repressor of Nrf2, can act as a sensor, directly binding EIAV-Rev upon EIAV infection and disrupting the binding of Keap1 and Nrf2, leading to the release and nuclear localization of Nrf2 and triggering the antioxidant response." (PMID 35139135, 2022). "PRV, rather than UV-PRV, infection increased Nrf2 protein level and decreased Keap1 protein level in a time- and dose-dependent manner." (PMID 40691814, 2025). "Such study showed that Keap1 was not degraded despite an increase in p62 protein levels, which suggests that S. aureus can manipulate p62 during an early phase of infection by reducing the phosphorylation levels of p62 at Ser349." (PMID 39763664, 2024). "Consistent with a central role for oxidative stress responses in cell-intrinsic responses to infection, key antioxidant enzymes (GSR, CAT, GPX1, and PRDX1) were downregulated by YFV-17D and select genes (SOD2, NFE2L2, and KEAP1) were upregulated by MnTBAP treatment." (PMID 39282299, 2024). "In response to various stressors such as infection, NRF2 dissociates from KEAP1 and translocates to the nucleus to activate transcription of its downstream targets, including genes involved in glutathione and lipids metabolism, detoxifying and antioxidant pathways and mitochondrial function." (PMID 37956169, 2023). "While knockdown of KEAP1, GPR89A/B, and SPNS1 initially decreased interferon stimulation in our experiments, it is conceivable that these factors have a secondary role in protecting the population from infection in long-term cultures." (PMID 37803001, 2023). "On the other hand, the expression of KEAP1 mRNA, which interacts and negatively regulates NRF2, has an initial decrease in expression (24 h) compared to control cells and is increased later during infection (72 h)." (PMID 33826673, 2021). "However, the absence of KEAP1 did not reduce the capacity of 4-OI to increase VSVΔ51 infection in 786-O cells." (PMID 38750019, 2024).
infection (continued). "However, Keap1 stability is decreased in a PKR-dependent manner between 2 and 4 h of infection." (PMID 28959260, 2017). "KEAP1, GPR89A/B, and SPNS1, which were previously found to be protective when knocked out5,7,9, did not alter infection dynamics within our study." (PMID 37803001, 2023). "Altogether, ARP101 treatment may result in a feedback loop via the noncanonical Keap1-Nrf2 signaling pathway, which is responsible for increased levels of p62 despite increased LC3 II levels later during infection." (PMID 36939350, 2023).
adenocarcinoma (29 papers, 2013 to 2025). A common cancer characterized by the presence of malignant glandular cells. "Keap1 mutations were predominantly identified in patients with a history of heavy smoking and advanced adenocarcinoma." (PMID 24137397, 2013). "Keap1 mutations were identified in 2 (2.6%) adenocarcinoma patients with a history of heavy smoking." (PMID 24137397, 2013). "Notably, these results were limited to the KRAS wild-type squamous cell carcinoma and adenocarcinoma, whereas in adenocarcinoma histotype the effect of epigenetic silencing of KEAP1 was also observed in the EGFR mutated subpopulation." (PMID 35004317, 2021). "CL7 included only combined adenocarcinomas, most of which harbored mutations in KRAS and/or KEAP1 and STK11." (PMID 40144596, 2025). "KRAS, BRAF, STK11/KEAP1, MUTYH/RET, and RBM10/MET-associated modules showed the opposite trend, having significantly higher frequencies of adenocarcinoma cases as genomic alterations increased (P ≤ 0.02)." (PMID 39664186, 2024). "Inasmuch as TNFα-NFκB pathway was enriched in KEAP1 R320 and R470 adenocarcinoma samples in our GSEA analysis, we analyzed the expression of two NFκB target genes, IL23A and BIRC2, in transduced cells." (PMID 38184997, 2024). "So in this paper, we discuss results preliminary, but very intriguing: we analyze the effect of Keap1 silencing on HSP90 pathway in an in vitro model RAW264.7 cells treated with LPS and in A549, a Keap1 mutated adenocarcinoma cell line." (PMID 35362892, 2022). "In an analysis of 533 NSCLC adenocarcinoma patient records from the TCGA portal, PTGR1 was found to be highly expressed in KEAP1 mutated samples." (PMID 33889302, 2021). "A549 cells are derived from an adenocarcinoma of human alveolar basal epithelium and exhibit aberrant activation of NRF2 owing to two mechanisms: one is a somatic mutation in Keap1 at G333C and the other is the epigenetic silencing by methylation in the promoter of Keap1." (PMID 34566633, 2021). "Interestingly, in the GSEA analysis with the TCGA adenocarcinoma cohort, several BIRC family of genes were enriched in KEAP1 R320 and R470 mutant samples." (PMID 38184997, 2024). "The third NSCLC patient with SD was immune checkpoint inhibitor-naïve, had PD-L1 negative adenocarcinoma, and no KRAS/STK11/KEAP1 alteration was seen." (PMID 41523436, 2025). "A previous study demonstrated that low or absent Keap1 expression is common in NSCLC (56%), largely in adenocarcinomas." (PMID 24137397, 2013).